RGS5 (regulator of G protein signaling 5)
Diseases named in the same sentence as RGS5 in open-access papers (continued):
Sharing a sentence is not in itself a finding about the gene and the disease.
tumor (continued). "Therefore, RGS5 levels could be expected to vary according to the extent and stage of tumor vascularization, perhaps explaining the gene expression variability for RGS5 among single-biopsy specimens." (PMID 22792465, 2012). "Canonical markers were used to annotate different cell types: malignant cells (COL1A1, IBSP), myeloid cells (CD74, CD14), osteoclasts (CTSK, MMP9), pericytes (RGS5, ACTA2), endothelial cells (PECAM1, VWF), and tumor-infiltrating lymphocytes (CD3D, NKG7)." (PMID 40730548, 2025). "For stromal cells, we identified four mural cell subclusters (CCL19+ pericytes, RGS5+ pericytes, COL4A1+ smooth muscle cells [SMCs], and MYH11+ SMCs) and two EC subclusters (peripheral ECs and tumour core ECs)." (PMID 38943472, 2024). "Tumor promoting CAFs displayed high expression of CCDC80, SFRP2, VCAN, COL8A1, RGS5, HIIGD1B, NOTCH3, and NDUFA4L2." (PMID 38525245, 2024). "Regulator of G-protein signaling 5 (RGS5) inhibits TDPs maturation, and its knockout results in enhancing CTL infiltration and extending the survival of tumor-bearing mice." (PMID 36646951, 2023). "Furthermore, tumor-derived RGS5 could be transferred into VSMCs." (PMID 37986113, 2023). "Tumor derived PCs inhibit CD4+ T cell proliferation and activation while promoting CD4+ T cell anergy in vitro, which is also regulated by RGS5- and IL-6-dependent signaling pathways (process ➃)." (PMID 34179005, 2021). "Upregulation of PD‐L1, CD90, PDGFRβ, CD248 and Rgs5 which inhibit CD4+ and CD8+ cytotoxic T‐cell activity was reported in pericytes derived from within tumour microenvironments, which facilitates immunosuppression and eventual immune evasion of tumour cells." (PMID 32588948, 2020). "Among the various populations of tumor‐residing non‐hematopoietic stromal cells (NHSCs) functionally altered pericytes (cells wrapping blood capillaries) show strong expression of pro‐apoptotic molecule, ‘regulator of G‐protein Signaling 5′ (RGS5) which may confer its immunoregulatory phenotypes." (PMID 29460395, 2018). "Non-tumor components included endothelial cells (expressing VWF, CDH5, ECSCR, SLCO2A1, and MYCT1), pericytes (marked by RGS5, MCAM, and PDGFRB), normal oligodendrocytes (showing PTGDS, MBP, TF, and MOG expression), and TAMs (identified by CD14, AIF1, FCER1G, FCGR3A, TYROBP, and CSF1R)." (PMID 41394801, 2025). "The results identified two major trajectories: RGS5+ fibroblasts and MYH11+ fibroblasts acted as progenitors, whereas STEAP4+ fibroblasts and Tumor-like fibroblasts represented transitional states, terminally evolving into ECM-remodeling fibroblasts or C7+ fibroblasts." (PMID 40520021, 2025). "After treatment with CM from tumor cells, LX2 cells transformed from spindle shaped to radial, with increased protrusions, upregulated activation marker (ACTA2, COL1A1, DES) expression, and downregulated quiescence marker (RGS5) expression." (PMID 41214328, 2025). "The upregulation of LRP1B, RGS5, STAT2, and HLA-A in SDR42E1-depleted cells suggests enhanced apoptotic singling, tumor-immune crosstalk, and immune recognition—aligning with vitamin D’s immunomodulatory roles and potentially increasing chemotherapy sensitivity." (PMID 40756515, 2025). "Effector T cells reduced tumor growth in the absence of the Rgs5 gene with no additive trametinib effects." (PMID 39286984, 2024). "While these results are encouraging and innovative, our data indicate that PDAC tumor-associated pericytes and PDAC Exo-treated pericytes do not express significant levels of Rgs-5, emphasizing pericyte heterogeneity across the different types of tumors." (PMID 35626052, 2022). "They suggested that these tumor-suppressive effects are independent of the role of RGS5 in vascular normalization and remodeling." (PMID 34748583, 2021). "NLGP therapy downregulates TGFβ without affecting RGS5 in pericytes which support sustained tumor growth restriction." (PMID 29460395, 2018).
tumor (continued). "Moreover, tumor-derived pericytes were able to induce CD4+ T cell anergy and this effect was rescued after Rgs5 silencing." (PMID 26000022, 2015). "Since PDL-1 expression in cancer cells is known to inhibit the activity of PD-1+/CD8+ T cells, the combined effects of RGS5 and PDL-1 expression in pericytes may improve protection of tumor cells from T cell-mediated death." (PMID 26000022, 2015). "In human RCC, RGS5 was detected specifically in the tumor vessels, but not in the tumor cells or in the normal capillaries within the renal parenchyma." (PMID 26300785, 2015). "Out of these, we have chosen three most changed in LSCCs namely RGS5 (fold change 0.08), MAF (fold change 0.15), and ITPR2 (fold change 0.3) which are attractive candidates for novel tumor suppressors according to their function and involvement in other cancers." (PMID 26694163, 2015). "Interestingly, in addition to Rgs5, upregulation of PDL-1 was also observed in pericytes cultivated in the presence of tumor fragments." (PMID 26000022, 2015). "Although not statistically significant, the RGS5 knockout mouse model resulted in the opening of solid tumors to spontaneous immune effector T-cell infiltration into the tumor parenchyma." (PMID 22792465, 2012). "However, further study needs to be carried out to determine the level of RGS4 and RGS5 expression in other types of cancer and explore whether RAD6A/B can regulate the RGS proteins in cancer cells to induce tumor progression." (PMID 34199813, 2021). "In addition, when we considered the tumour status of the patients, again tumour-free patients have a higher RGS5 expression level than with-tumour patients regardless of their WBC counts." (PMID 32431860, 2020). "Finally, the histological tumor samples of the control mice showed areas of skin ulceration, whereas the RGS5-expressing sections did not." (PMID 22792465, 2012). "The molecule Regulator of G protein Signaling 5 (RGS5) is specifically expressed in platelet-derived growth factor receptor β-positive (PDGFRβ)+ immature pericytes during the angiogenic switch and further up-regulated in a highly angiogenic and hypoxic tumor environment." (PMID 24213314, 2012). "Nitric oxide and Rgs5 have been revealed as key regulators and the haplodeficiency of Egln1 within host mice (i.e. not within engrafted tumor cells) also influenced intra-tumor capillary structure." (PMID 22905089, 2012). "Furthermore, the increased expression of RGS5,a regulator of vascular maturation, and FTH1,involved in iron metabolism, implies a supportive role for EC5 cells in maintaining endothelial integrity and remodeling the tumor microenvironment to favor metastatic colonization." (PMID 41394809, 2025). "Immunofluorescence staining also showed that RGS5 was mainly enriched in the wall of and around the arterioles in TNBC tissues, suggesting that RGS5 expression in VSMCs increased in the context of the tumor microenvironment, which may be involved in remodeling of the vasculature in tumor." (PMID 37986113, 2023). "Using scRNA-seq on tumor samples and para-tumor samples from bladder carcinoma and the sequencing data from TCGA, investigators found that the iCAF-specific marker PDGFRA was associated with poor overall survival while the myo-cancer-associated fibroblast marker RGS5 was not." (PMID 36830713, 2023). "Taken together, these data support the hypothesis that RGS5 is associated with fibrosis and HSC activation in both tumor and non-tumor associated fibrosis, and that the observed up-regulation of RGS5 expression in fibrotic liver tumors may be due to tumor associated activated HSCs." (PMID 25290689, 2014). "Even though it had no significant inhibitory effect in tumor growth, BYHWD effectively normalized the tumor microenvironment and vasculature by modulating VEGF, regulator of G protein signaling 5 (RGS-5) and HIF-1α." (PMID 33801741, 2021).
tumor (continued). "To verify if the observed downregulation of MAF, ITPR2 and RGS5 was characteristic also for primary LSCC specimens, we analyzed group of 22 tumors and five no tumor controls by quantitative real time PCR." (PMID 26694163, 2015). "In this model where Rgs5 is inactivated, adoptive T-cell transfer results in massive infiltration of CD8+ and CD4+ lymphocytes within the tumor, whereas wild type tumors showed no significant increase of intratumoral immune cells." (PMID 24765614, 2014).
cancer (55 papers, 2011 to 2025). A tumor composed of atypical neoplastic, often pleomorphic cells that invade other tissues. "In HCC, tumor cells lacked EPCAM and expressed complement and stem cell markers; cancer-associated fibroblasts (CAFs) were scarce, and stellate cells expressed the pericyte marker RGS5." (PMID 41228323, 2025). "Recent studies have shown that RGS5 is expressed in skin wound fibroblasts and cancer-associated fibroblast (CAF) subpopulations." (PMID 38890483, 2024). "A recent study used scRNA-seq on primary and untreated peritoneal metastatic sites and identified a subset of RGS5+ cancer-associated fibroblasts (CAFs) strongly supporting tumor metastasis and cancer recurrence in EOC." (PMID 38328306, 2023). "One of them is the RGS5+ fibroblast, which has characteristics similar to those of cancer-associated myofibroblasts." (PMID 36463319, 2022). "Briefly, myeloid cells (LYZ+), lymphocytes (CD3D+), osteoclasts (ACP5+), endothelial cells (CLDN5+), perivascular-like cells (PVL) (RGS5+TAGLNhigh), cancer-associated fibroblasts (CAFs) (TAGLNlowACTA2+) and proliferative cells (MKI67+) were identified in the study." (PMID 36596773, 2023). "In particular, the metastatic ecosystem was found to feature remarkable reprogramming of immunosuppressive cells such as FOXP3+ Treg cells, LAMP3+ tolerogenic DCs, CCL18+ M2‐like macrophages, RGS5+ cancer‐associated fibroblasts (CAFs), and LGALS1+ microglial cells." (PMID 36529697, 2023). "ER+ tumors are characterized by changes in the stromal compartment, with enrichment of endothelial cells (endo ACKR1, CXCL12, RGS5) and depletion of cancer-associated fibroblasts (iCAFs2 and myCAFs4), inflammatory monocytes (Mon S100A9), and B naive cells, compared with TNBC." (PMID 37549298, 2023). "Furthermore, several immunosuppressive cells were identified to reprogram the metastatic ecosystem, including FOXP3+ regulatory T (Treg) cells, LAMP3+ tolerogenic DCs (tDCs), CCL18+ M2‐like macrophages, RGS5+ cancer‐associated fibroblasts, and LGALS1+ microglial cells." (PMID 36529697, 2023). "The proportion of RGS5-positive pericytes within fibroblast-lineage cells was relatively high in both less aggressive cancers (such as TC and BC) and low in highly aggressive ones (such as ESCC and PDAC)." (PMID 41228323, 2025). "Cancer-associated fibroblasts were clearly divided into three clusters, and their marker genes were DCN, FAP and RGS5." (PMID 37963845, 2023). "Here, the volcano plot analysis sheds light on some genes, including RGS5, BBOX1, PKHD1L1, and TXRND3, that are associated with cancer." (PMID 36790468, 2023). "The dominant populations of cancer-related myofibroblasts and fibroblasts include RGS5-expressing myofibroblasts and CXCL14-expressing fibroblasts." (PMID 36463319, 2022). "Immunohistochemical staining for RGS5 in 60 HCC patients shows that the protein level of RGS5 in cancer tissues of HCC patients is 63.3% higher than that in paired noncancerous tissue." (PMID 35036167, 2021). "Cluster 0 cells showed fibroblast signatures (RGS5 and NDUFA4L2), cluster 2 cells had strong expression of cancer associated fibroblast (CAF) markers (LUM, SFRP4, and COL1A1), and cluster 5 cells expressed myofibroblast markers (MYH11, TAGLN, and ACTA2)." (PMID 33662621, 2021). "The RGS5 gene codes for a cytoskeleton regulating protein that can mediate an epithelial-mesenchymal transition in cancer cells and was previously found to be differentially expressed and up-regulated in endometrial mesenchymal stem cells." (PMID 28125717, 2017). "Previous studies reported that several RGS proteins, including RGS2, RGS4, and RGS5, were involved in cancer development." (PMID 28724429, 2017). "Finally, normal D and cancer 3 retained common markers of CAPs, including RGS5, MCAM, and CRIP1, pathways relating to contractility and cytoskeletal rearrangements, and activity of transcription factors associated with muscle contractility, including MYOG." (PMID 40215177, 2025).
cancer (continued). "For example, the stromal subset consisted of endothelial cells identified by expressions of VWF, PECAM1 and KDR, pericytes with high RGS5, ACTA2, and COL4A1 expressions, and cancer-associated fibroblasts (CAFs) identified by significant expressions of COL1A1, DCN and LUM." (PMID 38925650, 2024). "And then, the Lenti-RGS5-infected cancer cells were co-cultured with VSMCs." (PMID 37986113, 2023). "In addition, RGS5 was known to promote cancer differentiation and metastasis in NSCLC, which was also enhanced in C3." (PMID 36483553, 2022). "Moreover, BM-derived CAFs did not express high levels of αSMA and therefore are unlikely contributors to the dominant αSMA and Rgs5-expressing CAFs in late PyMT carcinomas." (PMID 31505876, 2019). "Several studies have examined the relationship between RGS5 and carcinoma." (PMID 31049219, 2019). "Misexpression of RGS2, RGS4, and RGS5 has also been reported in a number of these cancers." (PMID 23637832, 2013). "Looking more broadly at the gene expression of RGS5 in malignant tumors produces mixed results." (PMID 22792465, 2012). "Furthermore, the staining pattern of RGS5 coincided with vessel-like structures, which is suggestive of a biomarker for cancer vasculature and consistent with RGS5 expression predominantly resulting from the vascular endothelium of carcinoma." (PMID 22792465, 2012). "We also analyzed the transition of CSFs in separate cancer types, and found that in BC, CRC and OVC, CSFs were mainly transformed from DPT+ fibroblasts, while in ICC, CSFs were mainly transformed from RGS5+ FBs." (PMID 36744260, 2023). "We constructed a multi-cancer fibroblast atlas, in which fibroblasts were classified into six clusters: BAMBI+ FBs, CLDN1+ FBs, COL11A1+ FBs, CXCL14+ FBs, DPT+ FBs and RGS5+ FBs." (PMID 36744260, 2023). "It’s more interesting that when analyzing the origin of CSFs in separate cancer types, we found that CSFs were mainly transformed from DPT+ FBs in BC, CRC and OVC, while mainly from RGS5+ FBs in ICC." (PMID 36744260, 2023). "Mechanistically, ZNF750 suppresses the expression of some cancer-related genes such as angiogenin, VEGF, RGS5, CD105, ITGA5, ITGB1, and CD44." (PMID 34288812, 2021). "Down-regulation of RGS5 induces GPCR-mediated signaling pathways and promotes migration of vascular and cancer cells." (PMID 24427155, 2013). "RGS5 could inhibit the activation of Gαq and Gαi subunits of G protein and then hinder the EMT of cancer cells." (PMID 31049219, 2019). "Because the invasion and metastasis of cancers are related to epithelial‐mesenchymal transition (EMT), we carried out staining for N‐cadherin, vimentin, and E‐cadherin to examine the relationship between EMT and RGS5." (PMID 31049219, 2019). "In addition, our comparative analysis revealed that CAFs and pericytes could be clearly distinguished in most cancers except HCC based on DCN (a CAF marker) and RGS5 (a pericyte marker)." (PMID 41228323, 2025). "Additionally, while RGS5 is frequently identified in CAF populations including in other cancers, RGS5 CAF function is not well defined." (PMID 38525245, 2024). "Since there are not many patients with stage 2 and 4 cancer, one may ignore the T2–T3 and T3–T4 differences and conclude a significant decrease in the RGS5 expression level from T1 to T3." (PMID 32431860, 2020).
infection (4 papers, 2021 to 2025). The state of being infected such as from the introduction of a foreign agent such as serum, vaccine, antigenic substance or organism. "Vascular cells shared six down-regulated DEGs in response to either Aβ pathology or MA10 infection, (Rgs5, Slc1a2, Flt1, Sparcl1, Bsg, Pecam1)." (PMID 41497643, 2025). "We investigated ARG2, RGS4, and RGS5 protein expression by western blot analysis of whole cell lysates extracted from BHP18-21v cells 72 h after 300 MOI AdLacZ or AdNKX2-1 infection." (PMID 34748583, 2021). "For further investigation, we selected three genes, ARG2, RGS4, and RGS5 based on the following criteria: there was an apparent expression 6 h after infection, the ratio 12 h after infection was more than twice, and the ratio 24 h after infection was >10-fold." (PMID 34748583, 2021). "Moreover, Gene Ontology (GO) enrichment analysis showed that Rgs5-null astrocytes were much less inflamed following LPS challenge, as the top 20 biological pathways most significantly enriched among the genes that differed were related to infection, inflammation and immunological response." (PMID 37674228, 2023). "ARG2, RGS4, or RGS5 expressions were not induced 72 h after 30, 100, 300, and 1000 MOI AdNKX2-1 infection in HepG2 cells." (PMID 34748583, 2021).
inflammation (1 paper, 2021). Aberrant reaction of the microcirculation characterized by movement of fluid and leukocytes from the blood into extravascular tissues. "In two independent animal models, bleomycin- and LPS-induced acute lung inflammation, we show that RGS5 loss attenuates lung function disorders in the acute inflammatory phase which can be explained by blunted neutrophil recruitment." (PMID 34502263, 2021).
neurodegenerative disease (1 paper, 2023). A disorder of the central nervous system characterized by gradual and progressive loss of neural tissue and neurologic function. "Blockade of the astrocytic RGS5/TNFR interaction is a potential therapeutic strategy for neuroinflammation-associated neurodegenerative diseases." (PMID 37674228, 2023). "The development of a therapeutic strategy, that blocks the interaction between RGS5 and TNFRs, may effectively limit chronic neuroinflammation, thereby interfering with the progression of neurodegenerative diseases." (PMID 37674228, 2023).
RGS5 also shares sentences with these, for which no sentence is quoted: prostate carcinoma (3 papers); infantile hemangioma (2); Insulin resistance (2); myopia (2); Parkinson disease (2); acute myeloid leukemia (1); airway hyperresponsiveness (1); Alzheimer disease (1); asthma (1); brain diseases (1); brain tumor (1); diseases of Huntington’s (1); dyslipidemia (1); endometriosis (1); glioblastoma (1); Glucose intolerance (1); hyperlipidemia (1); insulinoma (1); invasive breast carcinoma (1); left ventricular dilation (1); liver (1); metabolic disorders (1); Myocardial fibrosis (1); neurological disorders (1); pancreatic cancer (1); pancreatic neuroendocrine tumor (1); plasmacytoma (1); portal hypertension (1); renal disease (1); steatosis (1).
A further 3 diseases each share a sentence with RGS5 in 1 paper.